TMEM161A (transmembrane protein 161A)
Description:
May play a role in protection against oxidative stress. Overexpression leads to reduced levels of oxidant-induced DNA damage and apoptosis.
Synonyms: AROS-29; FLJ39645; FLJ20422; AROS29
Tractability: Antibody: UniProt predicts a signal peptide or a membrane-spanning region. PROTAC: ubiquitination databases record sites on it.
Gene: Protein-coding gene on chromosome 19 (19,119,169 to 19,138,513, reverse strand). Ensembl gene ENSG00000064545.
Subcellular location: Membrane
Subcellular location (Human Protein Atlas): Cytosol
Gene Ontology:
Molecular function: protein binding
Biological process: cellular response to oxidative stress; cellular response to UV; negative regulation of intrinsic apoptotic signaling pathway in response to DNA damage; positive regulation of DNA repair; response to retinoic acid
Cellular component: membrane
Genetic constraint (gnomAD): Loss-of-function variants: 45 observed, 53.3 expected, observed/expected ratio (o/e) 0.84, 90% interval 0.66 to 1.08. The upper end of that interval is the gene's LOEUF score, 1.08, which puts it in group 4 of 6, group 1 being the genes least tolerant of losing a copy. Missense variants: 578 observed, 567.71 expected, observed/expected ratio (o/e) 1.02, 90% interval 0.95 to 1.09. Synonymous variants: 280 observed, 257.14 expected, observed/expected ratio (o/e) 1.09, 90% interval 0.99 to 1.2.
Homologues: Orthologues: chimpanzee TMEM161A (99% identical), macaque TMEM161A (97% identical), pig TMEM161A (91% identical), mouse Tmem161a (83% identical), guinea pig TMEM161A (79% identical), rat Tmem161a (77% identical), dog TMEM161A (72% identical), tropical clawed frog tmem161a (58% identical), zebrafish tmem161a (57% identical), Drosophila melanogaster emei (37% identical), Caenorhabditis elegans Y87G2A.13 (25% identical). Paralogues in human: TMEM161B (49% identical).
Diseases named in the same sentence as TMEM161A in open-access papers:
TMEM161A is named in the same sentence as 4 diseases in open-access papers, as found by Europe PMC text mining. Sharing a sentence is not in itself a finding about the gene and the disease. The quoted sentences say what the papers report.
non-small cell lung carcinoma (2 papers, 2023 to 2024). A group of at least three distinct histological types of lung cancer, including non-small cell squamous cell carcinoma, adenocarcinoma, and large cell carcinoma. "In a previous study on sharing TCRs in non-small-cell lung cancer, TMEM161A was identified as a novel tumor-associated antigen; its overexpression in tumors and its cross-reactive epitopes were from EBV LMP2A and E. coli." (PMID 38488909, 2024).
breast carcinoma (1 paper, 2022). "When missense variants were assessed, three further associations were observed for overall breast cancer (TMEM161A, SIPA1L1, ERCC2), and a further seven were observed for subtypes (RNF175, NCKAP1L, PHAX, SMARCA2, EML5, NTRK3, MED23)." (PMID 35884425, 2022). "There was modest evidence of an association with overall breast cancer risk for rare missense variants in three genes: TMEM161A (OR = 2.56 (CI 95% 1.19–5.51), p-value = 0.016), SIPA1L1 (OR = 1.68 (CI 95% 1.06–2.67), p-value = 0.026), and ERCC2 (OR = 1.45 (CI 95% 1.01–2.08), p-value = 0.047)." (PMID 35884425, 2022). "Analysis of rare missense variants identified evidence of associations of TMEM161A, SIPA1L1, and ERCC2 with overall breast cancer, RNF175 and NCKAP1L with ER-positive disease, and SLC22A10, PHAX, SMARCA2, EML5, NTRK3, and MED23 with ER-negative disease." (PMID 35884425, 2022). "The best putative candidates in this group were TMEM161A, ERCC2, and SIPA1L1 for overall breast cancer, RNF175 and NCKAP1L for ER-positive disease, and PHAX, SMARCA2, NTRK3, EML5, and MED23 for ER-negative disease." (PMID 35884425, 2022).
tumor (3 papers, 2022 to 2024). "More recently, tumor-infiltrating T cells in human lung cancer have been shown to cross-react with a tumor antigen derived from the TMEM161A protein and an antigen derived from the Epstein-Barr virus (EBV) latent membrane protein 2a." (PMID 37101139, 2023). "Moreover, tumor-infiltrating lymphocytes exhibit cross-reactivity against non-mutated TMEM161A tumor antigens and Epstein Barr virus (EBV) antigens." (PMID 36330482, 2022).
TMEM161A also shares sentences with these, for which no sentence is quoted: Autoimmunity (1 paper).